TLR2 (toll like receptor 2)
Diseases named in the same sentence as TLR2 in open-access papers (continued):
Sharing a sentence is not in itself a finding about the gene and the disease.
infection (continued). "Overall, compared with WT mice, TLR2−/− mice showed significantly more pronounced weight reduction on days 7 and 10 after infection." (PMID 36808423, 2023). "We noted a significant increase in the frequency of mb-TLR2+NK cells at all three post-infection time points (21 dpi: 12.6 ± 1.2%, p = 0.008; 90 dpi: 11.5 ± 0.9%, p = 0.004; 180 dpi: 10.9 ± 1.3%, p = 0.015) compared to the 0 day time point (5.5 ± 0.8%)." (PMID 38140264, 2023). "infection, but immunosuppressed mice showed significant differences in the expression of TLR2 at 16 and 24 dpi." (PMID 37242301, 2023). "Surprisingly, the responses of IgG subclasses to infection are controlled in different ways by aging and TLR2." (PMID 37258615, 2023). "miR146a-5p was predicted to be a negative regulator of B. burgdorferi-induced inflammation in early infection with mRNA targets including TLR2, STAT1, ICAM1, and IL6." (PMID 37319241, 2023). "In our investigation, we confirmed the elevation of TLR2 mRNA levels in long-term post-infection through Western blotting analysis." (PMID 37626956, 2023). "In this regard, we found that blocking TLR-2 or -4 prior to infection with M. tuberculosis decreased the production of TNF-α and IL-6." (PMID 36863206, 2023). "Bacterial lipoproteins and polysaccharides activate TLR2 in other infection models, but the chlamydial TLR2 ligand remains unidentified." (PMID 37662000, 2023). "In this regard, infection with L. pneumophila or S. pneumoniae markedly induced hBD2 expression in human pulmonary epithelial cells in a Toll-like receptor 2 (TLR2)/NF-κB-dependent manner." (PMID 37296737, 2023). "In vivo infection models demonstrated that the E protein induced TLR2-dependent inflammation in the lungs, and that blocking TLR2 signaling provided protection against SARS-CoV-2 induced pathology." (PMID 37175768, 2023). "Regarding the age factor, the only significant difference was observed between TLR2−/−/young and TLR2−/−/old mice on day 10 after infection." (PMID 36808423, 2023). "Treatment with a synthetic peptide, SPIKENET (SPK), which inhibits spike protein binding, reduced NGAL mRNA in acute infection, and decreased TGF-β1, BCL3 mRNA, EGFR, HIF1-α, and TLR-2 protein levels long-term post-MHV-1 infection." (PMID 37626956, 2023). "TLR2 mRNA expression remained consistently upregulated in six tissues after infection with CyHV-2, though it varied across tissues and at different times." (PMID 38003793, 2023). "Upon infection of TLR2-transfected HEK293 cells, UV-inactivated EBV particles strongly induce NF-κB activation and secretion of the chemokine monocyte chemoattractant protein-1." (PMID 37065193, 2023). "Collectively, these observations indicate that HylB promotes immune suppression in a TLR2/4- and IL-10-dependent manner to enhance the invasive potential of GBS during pregnancy-associated infections." (PMID 37747229, 2023). "Lower levels of TLR2, TLR4, TLR9, TRIF and Myd88 transcripts was associated with the infection of mice with high virulent T. cruzi strains." (PMID 36839554, 2023). "It is worth to increase the number of human studies to be performed on TLR2 response against the infection of Leptospira spp." (PMID 38014008, 2023). "Accordingly, pathogen secreting components and micro RNA can down regulate the TLR2 expression during infection." (PMID 38014008, 2023). "In the homogeneous environment of BMDM in cell culture, only a subpopulation of infected cells activated a TLR2-dependent inflammatory program upon infection." (PMID 37439558, 2023). "The expression of the tlr2, tlr9, nod1 and nod2 receptors in the gills did not change significantly after bacterial exposure when compared to controls (0 h), although a tendency to decreased tlr2 expression was seen at 6 and 24 h post-infection." (PMID 37731496, 2023).
infection (continued). "Of note, two recent studies show that co-activation of multiple CLEC5A- and TLR2-mediated pathways are required for optimal host innate immunity against infection with DV or Listeria monocytogenes." (PMID 37872182, 2023). "TLR2 is reported to regulate the initial pro-inflammatory response during infection of macrophages with T. cruzi." (PMID 36937289, 2023). "Correspondingly, ROS production also showed a downward trend in cells pretreated with chloroquine (20 μM) or rapamycin (5 μM) following the knockdown of TLR2 in THP-1 macrophage infection." (PMID 37141335, 2023). "infection was observed as having increased expression of TLR2 and TLR4 at the beginning of infection." (PMID 37242301, 2023). "As found with the LVS, TLR2 signaling was required for the increased cytotoxicity and decreased intracellular replication observed during infection with the Schu S4 ∆tolC mutant." (PMID 37404047, 2023). "Platelets express functional TLR2/4 and MyD88, which participate in platelet responsiveness to infection." (PMID 37885890, 2023). "It has been shown that even short-term infection with microbial pathogens can promote TLR2 activation and presumably contribute to a short-term increase in viral load in patients with HIV." (PMID 37606452, 2023). "In line with previous findings, we showed higher fold changes in IL-6 levels after infection in TLR2−/−/young mice compared with WT/young mice." (PMID 36808423, 2023). "The toll-like receptor signaling pathway was highly enriched at 48 hpi, showing that Tlr2 and Tlr3 were upregulated during infection." (PMID 37963152, 2023). "We first addressed the contribution of TLR2/TLR4 to the production of these antimicrobial compounds upon infection with leptospires." (PMID 35899053, 2022). "HBeAg, not HBcAg, inhibited p38 phosphorylation in response to both LPS and Pam3Csy, suggesting that HBeAg is able to interfere with both TLR4 and TLR2 activation during infection." (PMID 36680092, 2022). "The results were confirmed by the mean fluorescence intensity analysis, and the MFI for TLR2 had a significant value at 2, 6 and 10 h post-infection." (PMID 35628694, 2022). "Not only do inhibition of TLR2 and autophagy by Mtb reduce the innate immune response to infection, but we also observed inhibition of adaptive immune responses." (PMID 35467412, 2022). "It has also been demonstrated that MBL reacts with TLR2 during infection with Staphylococcus aureus." (PMID 35630457, 2022). "Two days after infection, the mice treated with TLR2 inhibitors had obviously reduced release of inflammatory factors such as IL-6 and MCP-1, and the survival rate of SARS-CoV-2-infected mice was obviously improved." (PMID 36389144, 2022). "We observed that leptospires triggered the production of ROS 6 h post-infection and that it was dependent on TLR2/TLR4." (PMID 35899053, 2022). "TLR2 has been shown to play a protective role during infection by triggering a strong pro-inflammatory response, which is considered as beneficial for bacterial clearance." (PMID 35205112, 2022). "Taken together, these observations suggest that the dual loss of TLR2 and TLR9 significantly reduces reactive callus formation during infection." (PMID 36226943, 2022). "The possible reason for this is that the reduction in TLR2 surface expression after infection is due to the release of soluble proteins; this results in higher levels of soluble TLR2 under certain infectious and inflammatory processes." (PMID 36171749, 2022). "We infected RANKL-primed BMDMs from WT, Tlr2−/−, Tlr9−/−, and Tlr2/9−/− mice and found that, for all genotypes, infection significantly increased osteoclast numbers compared to those observed in the vehicle." (PMID 36226943, 2022). "Alveolar macrophages from the nonsmokers group were the only ones to significantly increase TLR2 mRNA levels in response to PA infection (C vs. CP p < 0.05), whereas they remained unchanged in smokers, COPD, and COPD + ICS groups." (PMID 35897707, 2022).
infection (continued). "Upon infection, the activation of TLR2 and TLR4- mediated signaling pathways leads to lysosomal degradation of the bacteria." (PMID 36619761, 2022). "In this regard, the synthetic lipoprotein Pam3CSK4 or infection with live Staphylococcus epidermidis, both activating TLR2 signalling are used." (PMID 34750522, 2022). "Among them, TLR2, up-regulated only in CACs + PCR, constitutes a cell surface innate immune sensor that can recognize several viral proteins upon infection, including the SARS-CoV-2 protein." (PMID 35397534, 2022). "Even though the exact role of TLR2 in the context of bacterial clearance in mouse infection models of A. baumannii remains to be resolved, our study reveals the activation of the TLR2 signaling pathway with an A. baumannii secreted lipid." (PMID 35615509, 2022). "To assess this further, we examined the effects of the TLR2 agonist Pam3CSK4 during Mφ::51 infections with Msm." (PMID 35467412, 2022). "At the early infection stage, TLR2 enhances the entrance of Mtb bacteria into macrophages by binding PE_PGR33, a mycobacterial protein from the Mtb." (PMID 35205112, 2022). "During infection with B. burgdorferi, TLR-2 expression is increased, therefore, EAAK linkers were used to merge Pam3CSK4 chain C to the N-terminus of the vaccine construct to increase TLR-2 expression." (PMID 36016127, 2022). "B. pseudomallei can be recognised by both TLR4 and TLR2, and this has been demonstrated in vitro, but in vivo TLR2 is responsible for the detection of LPS and host response to infection." (PMID 36271712, 2022). "In fact, comparing the susceptibility of TLR2‐/‐, TLR4‐/‐, TLR9‐/‐ and C57BL/6 WT to L. major infection, TLR9‐/‐ mice are most susceptible to this infection." (PMID 35119120, 2022). "Infection with M. gypseum induced a statistically significant upregulation of Dectin-1, TLR-2, and TLR-4 at 2, 5, and 14 dpi in the lung (p < 0.01); the peak of Dectin-1 emerged at 5 dpi, and TLR-2 and TLR-4 emerged at 2 dpi." (PMID 36233337, 2022). "TrpRS is secreted into the extracellular milieu by monocytes upon infection with certain pathogens and it interacts with TLR2 and TLR4 leading to the secretion of TNFα, neutrophil infiltration, and increased phagocytotic abilities." (PMID 35634293, 2022). "In MABS infection, MABS variants induce an innate immune response through TLR2-mediated IL-8 secretion." (PMID 36439147, 2022). "Combination of in vitro and in vivo data from this study demonstrates that L. infantum modulates TLR2 expression which participates in immune response against the infection." (PMID 35119120, 2022). "In vivo studies with L. chagasi suggested infection-mediated upregulation of TLR-2 and TLR-4 along with increased expression of IL-17, TNF-α, and IFN-γ during early hours of infection." (PMID 35531875, 2022). "The in vitro infection of monocytes with DENV-2 (16681 strain) demonstrated a slight increase in TLR2 expression on monocytes after 24h." (PMID 35632732, 2022). "The infection of C. perfringens increased the mRNA expressions of TLR-2, TLR-4 and NF-κB (P < 0.01) in jejunal mucosa, whereas the addition of EA in diets decreased the mRNA abundances of TLR-2, NF-κB (P < 0.01) and TLR-4 (P < 0.05)." (PMID 35436978, 2022). "While the survival rates of WT and Tlr2–/– mice were similar, all the Tlr4–/– mice died by 120 hours after infection." (PMID 36048544, 2022). "The meandering index of tlr2 mutant macrophages was lower than the tlr2 wild type macrophages in MAC 101 infection." (PMID 36741407, 2022). "Both staphylococci can activate the extracellular TLR2 to initiate the skin’s immune response against bacterial invasion and infection." (PMID 35281009, 2022). "In another animal experiment, K18-hACE2 transgenic mice were injected with TLR2 inhibitors during infection." (PMID 36389144, 2022).
infection (continued). "In the present study, we found that tlr2-/- zebrafish larvae showed a higher bacterial burden compared to their wild type controls after either M. marinum Mma20 or M. avium MAC 101 infection." (PMID 36741407, 2022). "The results suggest that potentiating the host immune response specifically by agonizing TLR2 protected mice from lethal infection of B. anthracis." (PMID 35369443, 2022). "Nevertheless, studies on children proved that H. pylori has the ability to promote the in vivo overexpression of different TLRs such as TLR2, 4, 5, and 9, early during infection, initiating a chronic and balanced inflammation." (PMID 35204842, 2022). "TLR2 has been shown to promote host survival in septic infections, but its role is less clear in tissue-specific models of infection (32, –, 38)." (PMID 36226943, 2022). "TLR2 has been found to sense various viral proteins after infection, including Epstein-Barr virus dUTPase, cytomegalovirus glycoprotein B, and hepatitis B virus capsid." (PMID 36171749, 2022). "A strong interaction between dietary APS and NE infection was observed in relation to TLR2, IFN-γ, TNF-α, IL-6, IL-10, RORα and Foxp3 (P < 0.05) in jejunum." (PMID 35265068, 2022). "While a consensus has not been made on which SARS-CoV-2 proteins activate which surface TLRs, several studies suggest that SARS-CoV-2 proteins contribute to detrimental cytokine storm via TLR2 or TLR4 associated with severe disease during infection." (PMID 36680092, 2022). "Here, we show that both TLR4 and TLR2 act in conjunction in macrophages to promote IFN-β gene expression upon infection, and that this is entirely dependent on PKR." (PMID 35154115, 2022). "Various pharmacological agents, including intra-nasal delivery of TLR2/6 agonist, are studied to prevent the entry of viruses and control the infection." (PMID 36052011, 2022). "Even though both cell types express Toll-like receptor (TLR) 2, the main TLR responsible for S. aureus detection, only osteoblasts were able to increase TLR2 expression after infection." (PMID 35935196, 2022). "Infection associated receptor encoding genes include CCR1 (encoding a receptor for CCL5), CRLF2 (cytokine receptor like factor 2), IL10RA, TLR2, CD2, CD48 and IL7R." (PMID 35061738, 2022). "To study the recruitment of macrophages and neutrophils to the sites of the infection, we used the tail fin infection model in both wild type and tlr2 mutants." (PMID 36741407, 2022). "In the Mma20 infection group, macrophages in tlr2-/- moved significantly slower than the macrophages in the wild type control group." (PMID 36741407, 2022). "Two homologous Brucella proteins (BtpA/TcpB and BtpB), translocated into host cells during infection, have been described to interfere with TLR2 and TLR4 signalling by inducing ubiquitination and degradation of the MAL/TIRAP adaptor molecule." (PMID 35888979, 2022). "In the current study, we focused on the function of PPE51 as a significant inhibitor of autophagy during infection and provide evidence linking this function to signaling through the innate immunity receptor, Toll-like receptor 2 (TLR2)." (PMID 35467412, 2022). "We previously reported that the expression levels of cxcl11aa and cxcll11ac after Mm infection was higher in 4 dpi tlr2+/- compared to 4 dpi tlr2-/- mutant zebrafish larvae." (PMID 36741407, 2022). "Using this system, we analyzed the function of tlr2 during the infection with both mycobacterial species with special attention to the responsive cell migration behavior." (PMID 36741407, 2022). "After 24 h of infection, the TLR2 and TLR4 mRNA expression levels were significantly decreased in the coaggregation group compared with the coinfection group (***p <0.001)." (PMID 35573793, 2022). "Induction of TLR2 and c-jun happens regularly during infections and can also be triggered by corticosteroids such as BUD and FLU." (PMID 35897707, 2022).
infection (continued). "Most importantly, the anti-inflammatory cytokine IL-10 is a key immunoregulator during infection and is induced in macrophages in vitro when TLR2 signaling is modulated during Candida albicans infection or after exposure to the human pathogenic Yersinia spp." (PMID 35638785, 2022). "By using a systemic model of TLR knock-out mice infection via the intraperitoneal route, TLR2 and TLR4 were shown to be dispensable for an efficient elimination of B. abortus." (PMID 35888979, 2022). "In terms of in vivo survivability, all vaccinated TLR2−/− mice fatally succumbed to WT infection post challenge at a nearly identical rate to unvaccinated TLR2−/− mice." (PMID 36229573, 2022). "Although these discrepancies remain unsolved till date, it is plausible that the L. donovani and L. major express different LPGs and thereby interacts with different heterodimers of TLR2 to trigger opposite outcomes of the infection." (PMID 35925884, 2022). "Our data suggest that in the infection phase, OmpA activates NF-κB-mediated inflammation through its epithelial receptor, TLR2, thereby contributing to high barrier permeability and bacterial translocation." (PMID 35844614, 2022). "At 24 hours post–planktonic infection, gene expression of TLR2 and TLR13 were upregulated, whereas expression of TLR2 and Complement component 7 was downregulated in the biofilm-infected group." (PMID 35677656, 2022). "We found that mice deficient in both TLR2 and TLR9 (Tlr2/9−/−) have decreased trabecular bone loss in response to infection compared to WT mice." (PMID 36226943, 2022). "To gain more insight into the mechanism underlying the TLR2-mediated production of TNF-α and IL-1β in monocytes, we pharmacologically targeted key molecules of signaling downstream of TLR2 prior to infection." (PMID 36240261, 2022). "In agreement, the expression levels of cxcl11aa and cxcl11ac were significantly lower in the tlr2 mutants after infection." (PMID 35205112, 2022). "Moreover, it needs to be investigated whether the changes of leukocyte migration behavior in tlr2 mutants are due to alterations of signals from the infection site or whether they are caused by cell-autonomous defects in the migratory abilities of the myeloid cells in the tlr2 mutant." (PMID 35205112, 2022). "In contrast, higher numbers of neutrophils were recruited in tlr2+/+ compared to the tlr2-/- MAC101 infection group although the difference in the number of neutrophils becomes smaller in the later stage of the tracking among the four groups." (PMID 36741407, 2022). "Cells were pretreated with small interfering RNA (siRNA) of TLR2 for 24 hr, and then treated with 500 ng/ml P2C, P3C (F) or heat-killed S. aureus (HK-SA) (multiplicity of infection [MOI] = 10) (G) (n=6 biologically independent samples)." (PMID 35762728, 2022). "This is surprising since the W83 strain induced a TLR2-dependent immune response in a mouse model of infection." (PMID 35432342, 2022). "Observations suggestive of involvement of TLR2/4 in pathogenesis of VL and induction of protection against infection post‐treatment." (PMID 35119120, 2022). "The results with Mma20 are consistent with what we have shown in our previous study with Mma20 infection in tlr2-/- zebrafish larvae." (PMID 36741407, 2022). "There we found that TLR2, IL6, OAT4, and CYP3A4 were significantly associated with the occurrence of infection." (PMID 33776761, 2021). "This reduction in TLR2 expression after trauma plus infection was also observed in PMN from lung, peripheral blood, and BM." (PMID 34520397, 2021). "C. albicans GDH18 infection led to enhanced mRNA expression levels of Dectin-2, TLR2, CCL2, and CXCL1/KC, compared with the levels in uninfected mice." (PMID 33919079, 2021). "The expression of TLR2, 3, 4, and 7 in splenocytes increased significantly after infection (p < 0.05)." (PMID 34788282, 2021).